EGFR (epidermal growth factor receptor)
Diseases named in the same sentence as EGFR in open-access papers (continued):
Sharing a sentence is not in itself a finding about the gene and the disease.
tumor (continued). "In tumors lacking EGFR expression, response to the targeted drug is unexpected regardless of accessibility, while in tumors with an EGFR overexpression, the accessibility of the tumor is expected to be a determining factor in drug uptake." (PMID 27965472, 2017). "Based on the morphology and genetic profiles, it was concluded that the right upper and lower lobe tumours were synchronous adenocarcinomas and the left lower lobe tumour a contralateral metastasis from the EGFR negative right lower lobe tumour (explaining the lack of effect of TKI treatment)." (PMID 28347348, 2017). "Numerous approaches using targeted therapies to limit tumor growth and neovascularization remain under evaluation including Bevacizumab, an anti-vascular endothelial growth factor (VEGF) antibody, and Erlotinib, a small molecule inhibitor of epidermal growth factor receptor (EGFR)." (PMID 29212208, 2017). "However, most of these studies were heterogeneous with regard to tumor stage and histology, and the data were not obtained from the era of EGFR-targeted therapy." (PMID 29228697, 2017). "The results presented here demonstrate that RHOB expression is predictive of EGFR‐TKI response and suggest that an EGFR‐TKI–AKT inhibitor combination may provide a clinical advantage to prevent resistance to EGFR‐TKI in RHOB‐positive tumor patients." (PMID 28003335, 2017). "In addition, we suggest new potential tumor-specific biomarkers that may improve on using NRG1 alone and allow for selection of a subset of HNSCC patients for the combination of KTN3379 with EGFR inhibitors." (PMID 28723928, 2017). "The changes in Kps and fPV in Moasser's data were temporary, as although a high dose of EGFR-TKI to improve tumor vascular hemodynamics is immediate, the histology may not change in the short period of time." (PMID 27852073, 2017). "Interestingly, the activity of EGFR was heterogeneous within the same untreated tumour section and did not depend on EGFR expression levels." (PMID 28166195, 2017). "However, panitumumab has no cross‐reactivity with mouse EGFR, which makes it difficult to assess the therapeutic window in tumor xenograft models." (PMID 28486761, 2017). "In situ examination of tumor tissues by IHC analysis demonstrated active EGFR (pEGFR) expression in both HPV‐positive and negative tumors with higher pEGFR positivity associated with HPV‐negative tumors (P = 0.033) and it negatively correlated with HPV infection status (OR – 0.27)." (PMID 28155253, 2017). "Here we focus on real-world treatment patterns and OS outcomes for people diagnosed with stage IV NSCLC without known EGFR or ALK tumor aberrations in the US community oncology setting during a contemporary time period just before immune checkpoint inhibitors entered standard of care in the US." (PMID 28644837, 2017). "Nevertheless, it was soon recognized that tumor-specific overexpression of the target molecule was not a prognostic marker of tumor treatment, as tumors that did not express detectable levels of the EGFR still reacted to antagonist treatment such as monoclonal antibody therapy." (PMID 28970798, 2017). "However, CTSB-positive non-macrophage cells were also detected (arrow) and found to overexpress EGFR (data not shown), which hints at their tumor origin." (PMID 28967558, 2017).
tumor (continued). "The tumor inhibition achieved with the anti-EGFR antibody cetuximab, though not statistically significant, was comparable to or less pronounced than EGFRvIII/CD3 TandAb, despite the fact that cetuximab was administered at a 10- to 100-fold higher dose (1 mg/injection) twice weekly." (PMID 28596941, 2017). "However, none of these EGFR conjugate studies has addressed whether these agents are effective in cancers, which are inherently non-responsive to individual or combinational therapies and whether anti-tumor efficacy is altered in tumor cells which harbor oncogenic mutations downstream of EGFR." (PMID 28572590, 2017). "An obvious biomarker, EGFR expression on tumor tissue, did not correlate with treatment benefit." (PMID 28695301, 2017). "Moreover, an endosomal accumulation of the activated EGFR does not increase tumour cell apoptosis but further increases tumour cell survival." (PMID 27387133, 2016). "As activation of mTOR has been shown to contribute in tumor progression, it can be speculated that the honokiol-induced inhibition of cell proliferation of HNSCC cells is mediated, at least in part, through the downregulation of EGFR/mTOR signaling pathway." (PMID 27886147, 2016). "Of note, all detected circulating tumor cells were epidermal growth factor receptor negative." (PMID 27465596, 2016). "One of the first compounds of this series was [18F]ML04, which although retained selectivity for EGFR in vitro was poorly specific in vivo, with high uptake in EGFR negative tumour models and no decrease in tumour radioactivity upon pre-treatment with a blocking dose of cold ML04." (PMID 27552105, 2016). "Additionally, EGFR gene amplification was more common in tumours of distal oesophagus (5/20 tumours, 25.0 %) and GOJ/cardia (13/63 tumours, 20.6 %) than in those of gastric corpus (2/65 tumours, 3.1 %) (χ2, p = 0.013)." (PMID 27387915, 2016). "The specific FDG uptake value could be considered to effectively predict EGFR mutation status of NSCLC patients by considering smoking history and primary tumor size when genetic tests are not available." (PMID 27472739, 2016). "Based on the “tumor cells repopulation” hypothesis, several clinical phenomenons were reported, including the restoration of EGFR-TKI sensitivity after EGFR-TKI withdrawal, disease flare after discontinuation of EGFR-TKI, and a better outcome for T790M-mutant patients." (PMID 27384480, 2016). "Thus, the expression of EGFR and HER-2 mRNA in these neoplasms may contribute to a better understanding of the progression mechanisms in malignant mammary tumors." (PMID 27490467, 2016). "Genomic analysis revealed neither an ALK gene rearrangement nor EGFR, BRAF or HER2 gene mutations, but an activating point mutation of the KRAS gene (p.G12C, exon 2) and therefore this tumor could be considered a non-responder case to EGFR-TKI therapy." (PMID 27548442, 2016). "However, if the background cells express a very low level of EGFR, the mutant EGFR expressed by the tumor cells will be highly enriched in RNA-sequencing, no matter how many background cells there are." (PMID 27352172, 2016). "Furthermore, combinational therapy targeting EGFR and IGF1R could synergistically inhibit cell viability, induce apoptosis in vitro and inhibit tumor xenografts growth in vivo." (PMID 27105537, 2016).
tumor (continued). "However, the influence of MCT1 on EGF-mediated motility in the absence of an effect on EGFR expression or activation highlights a more general mechanism of MCT1 regulation of growth factor-stimulated tumor cell motility." (PMID 27127175, 2016). "By contrast, anti-EGFR antibodies have not been able to provide survival benefit in clinical trials, which, however, have not included patient selection based on the histological subtype or EGFR gene copy number analysis of the tumours." (PMID 27387915, 2016). "However, this exclusive localisation has not been reported since in any study that analysed EGFR expression in this type of tumours." (PMID 28005997, 2016). "Importantly, patients with RAS mutant (MT) tumours showed no improvement in efficacy with the addition of EGFR inhibitor compared with chemotherapy alone." (PMID 27764839, 2016). "However, cellular radiosensitization by EGFR targeting is still a matter of discussion since some tumor cells show sensitization but others do not." (PMID 27281611, 2016). "However, while co-incubation with cetuximab did not result in a significant increase in COLO320 tumor cell death, a significant increase in killing was seen in four EGFR+ cell lines independent of RAS and BRAF status." (PMID 27314237, 2016). "Both tumor nodules are negative for KRAS and EGFR mutations (data not shown)." (PMID 27597976, 2016). "The clustering based on common pathways was independent of tumor EGFR status." (PMID 27354287, 2016). "Mutations affecting specific codons (so-called “hot-spot” codons) in exons 2, 3 and 4 of the KRAS and NRAS genes have been identified, which predict non-response to anti-EGFR mAbs and allow the further malignant proliferation of tumour cells, despite treatment." (PMID 27784278, 2016). "As BD-138T contains both EGFR amplification and PTEN deletion, we originally predicted that one or more of the EGFR inhibitors or mTOR inhibitors might be effective agents against this tumor." (PMID 27438149, 2016). "On EGFR-positive tumor xenograft specimens, the concentration ratio of EGFR-NPs vs. isotype-NPs rapidly increased to ~2.0 after three rinse steps, whereas the concentration ratio remained at unity for normal (EGFR-negative) tissues." (PMID 26878888, 2016). "INC280 showed preliminary anti-tumor efficacy as a single agent in 50% of patients with EGFR wild-type NSCLC with MET dysregulation, as confirmed by FISH (MET/centromere ratio ≥2.0 or MET gene copy number ≥5) or IHC (MET H-score ≥150 or 50% of tumor cells with a staining intensity of 2+ or 3+)." (PMID 27013592, 2016). "Cbl Y371F shows reduced EGFR ubiquitination in vitro and in cells, but it is significantly less efficient in promoting colony formation in soft agar assays and does not induce tumour formation when injected into mice." (PMID 27609087, 2016). "The failure of erlotinib to improve tumor control in the animal studies proves that this cell cycle arrest-dependent radiosensitization does not translate into improved tumor control and is therefore unlikely to contribute to a clinical effect of EGFR targeting in HNSCC patients." (PMID 27281611, 2016). "Importantly, tumour MMAE concentrations from CAL-27 xenografts injected with C-MMAE or T-MMAE confirmed restriction of released drug to EGFR+ cells by cetuximab conjugation as opposed to trastuzumab conjugation." (PMID 27698471, 2016). "Considering these discussion points, the reason that clinically important point mutations such as EGFR (L858R, T790M) and PIK3CA (E545K) discovered in tumor samples could not be observed in matched CTCs could be explained." (PMID 27892470, 2016). "Both tumor components were negative for BRAF and EGFR mutations (data not shown)." (PMID 27597976, 2016). "Our results also illustrate specific tumour detection of nanobody 99mTc-D10 to EGFR expressing tumour cells since no tumour uptake ex vivo and consequently no tumour uptake in vivo could be observed in the low EGFR expressing MDA-MB-231 tumour model." (PMID 26912069, 2016).
tumor (continued). "Conversely, promoting Madm nuclear translocation by expressing the hopTum−l or knocking down EGFR signalling will suppress integrin expression in CySCs, which will give GSCs the advantage of outcompeting CySCs for niche occupancy and will result in GSC tumour formation." (PMID 26792023, 2016). "All of the four circulating mRNAs, including CK7, ELF3, EGFR, and EphB4 mRNA, were strongly associated with NSCLC patients’ prognosis; however, the association of the cell-free RNA content with patient survival was independent of the tumor stage." (PMID 27827952, 2016). "In the present work, we convincingly showed that simultaneous targeting of both VEGF and EGFR could further suppress the proliferation and invasion of CRC cells in vitro, and further inhibit CRC cell tumor growth and angiogenesis through downregulation of AKT and ERK signaling in vivo." (PMID 27729020, 2016). "Moreover, scFv-9R/HER2si has no anti-tumor effect on EGFR-negative H69 cells, emphasizing the specificity of the anti-tumor effect of scFv-9R/HER2si on EGFR/HER2 dual positive tumors." (PMID 26988752, 2016). "Indeed, there is some evidence that EGFR inhibitors combined with FOLFOX in such patients are detrimental compared with FOLFOX alone, and EGFR inhibitors should therefore not be given to patients with RAS MT tumours." (PMID 27764839, 2016). "The main aim of this study was to determine whether NK cells and cetuximab could be combined to improve their anti-tumor efficacy and widen their applicability in mCRC independent of EGFR and RAS status." (PMID 27314237, 2016). "Furthermore, this sensitization was observed under experimental conditions (delayed plating) in which, for example, EGFR inhibitors failed to sensitize various tumor cell lines." (PMID 27015558, 2016). "This vector was found to be fast, effective and safe for the targeted delivery of lncRNA MEG3 RNA to the epidermal growth factor receptor (EGFR)-positive HCC cell lines without the activation of EGFR downstream pathways, and significantly attenuated both in vitro and in vivo tumor cell growth." (PMID 26992211, 2016). "Contrarily, in A549 and H441 xenografts models, lacking detectable EGFR shedding, low liver uptake was observed and tumor uptake could be saturated by 89Zr-imgatuzumab dose increments." (PMID 27602494, 2016). "Moderate/strong EGFR protein expression was found in 72/220 (32.7 %) and EGFR gene amplification in 31/220 (14.1 %) of the tumours, while moderate/strong HER2 protein expression was detected in 31/220 (14.1 %) and HER2 gene amplification in 29/220 (13.2 %) of the tumours." (PMID 27387915, 2016). "For example, interactions between the EGFR, IGF-1R and VEGFR signaling pathways are well established and target inhibition within one system commonly impacts molecular signaling (and ultimately tumor response) via compensatory response from companion RTK pathways." (PMID 27716204, 2016). "NGS: 23.7% detection rate in cfDNA, 61.5% detection rate in tumor tissue; 56.9% false negative rate for cfDNAProgression Free Survival (PFS): For patients positive for EGFR mutations, those who received gefitinib had longer PFS than those who received carboplatin-paclitaxel." (PMID 27589834, 2016). "Therefore, treatment with anti-EGFR mAbs previously only required confirmation of KRAS wild-type status; however, in 2013, the European Medicines Agency (EMA) revised the therapeutic indication, restricting it to patients with RAS wild-type mCRC tumours only." (PMID 27784278, 2016). "MiR-7 is a putative tumor suppressor in various solid tumors, and is reported to be down-regulated in NSCLC, which may suppress tumorigenesis by targeting a number of important proto-oncogenes and by inhibiting EGFR/AKT pathway activation." (PMID 27764812, 2016).
tumor (continued). "One might predict that these HER2‐amplified tumours would be resistant to cetuximab or panitumumab therapy, and that they may respond to targeted treatment against HER2, or a combination of therapies targeting HER2, EGFR and possibly also HER3." (PMID 26690310, 2016). "As nodal proteins, EGFR and survivin intersect multiple signaling networks, therefore targeting both molecules might lead to global pathway inhibition regardless of tumor heterogeneity." (PMID 27456457, 2016). "Moreover, the results from this study, based on immunohistochemical analysis of tumours from three independent patient cohorts, demonstrate that high EGFR protein expression is an independent negative prognostic factor in CRC patients." (PMID 27160084, 2016). "Except for EGFR mutations, the mutation frequency for the rest 19 differential SNV/InDels approximately equaled 50% or 100%, and these SNV/InDels were found in the tumor tissues of patients whose corresponding leukocytes were not sequenced due to the deficiency of the samples." (PMID 27001083, 2016). "Our findings of a correlation between EGFR gene mutations identified by the classifier and tumor response to EGFR-TKI treatment and such treatment’s lack of impact on OS were also consistent with previous studies in which EGFR gene mutation status was tested in tumor tissue." (PMID 26047516, 2015). "Thus, primary EO771 and EO771.LMB tumours were analysed by immunohistochemistry for markers of the luminal A/B subtypes (ERα, ERβ, PR), the HER2 subtype (Erb-b2/Neu) and the basal-like subtype (KRT5/6, EGFR) and compared to 67NR and 4T1.2 tumours." (PMID 25633981, 2015). "Furthermore, the specific antibodies only targeted a subpopulation of EGFRvIII-positive cells; they did not affect subsets of tumor cells with wild-type EGFR or other mutant receptor forms." (PMID 28347118, 2015). "Thus, by simultaneous inhibition of HDAC and the EGFR downstream pathway, CUDC-101 may offer a potential treatment for overcoming tumor resistance in ATC therapy." (PMID 25940539, 2015). "However, if expression of both mutant EGFR and mutant KRAS is detrimental, co-mutated cells are unlikely to survive during tumor evolution; therefore, they are unlikely to explain TKI resistance in an EGFR-mutant tumor." (PMID 26047463, 2015). "Nine IBC cases were p-EGFR negative in tumor and one was p-EGFR negative in stroma." (PMID 25887413, 2015). "Indeed, we found that combining Lapatinib, a dual EGFR/HER2 inhibitor, with ENZ most effectively reduced cell viability in LNCaP cells in vitro and suppressed tumor growth vivo, supporting previous findings showing HER2 inhibition augments the therapeutic effect of androgen deprivation in PCa cells." (PMID 25871401, 2015). "Likewise the tumour specific expression of the RAGE binding proteins lectin, galactoside-binding, soluble, 3 and CAPZA1 in tumours of EGF transgenic mice is highly suggestive for a sustained crosstalk between RAGE and EGFR." (PMID 25872475, 2015). "Interestingly, 36% of cases were GLUT1-negative despite their EGFR-mutant status, suggesting that glucose transporters other than GLUT1 might be operating in such tumor tissues." (PMID 26023239, 2015). "In addition, patients with ESCC expressing high levels of EGFR had a better OS than patients with an ESCC tumor with low EGFR expression, although this difference was not statistically significant." (PMID 26392415, 2015). "However, it is unknown whether mPGES-1/PGE2 signalling modulates EGFR expression levels.We measured EGFR expression in DU145 mPGES-1SC and mPGES-1KD cells, in tumours from mice inoculated with the respective cell lines and in DU145 and PC-3 treated with MF63." (PMID 26113609, 2015). "The tumour tissue investigated for EGFR expression is usually the primary tumour sample, however, this may not reflect the molecular landscape and immunohistochemical profile of the metastatic site." (PMID 26149458, 2015).